PGR (progesterone receptor)
Diseases named in the same sentence as PGR in open-access papers (continued):
Sharing a sentence is not in itself a finding about the gene and the disease.
breast cancer (continued). "Although oestrogen and progesterone receptor positivity in the gastric biopsies suggest breast cancer metastasis to the stomach, it is worth noting that oestrogen and progesterone receptor positivity have been reported in 32% and 12% of patients with primary gastric cancer." (PMID 17620117, 2007). "Therefore, testing for estrogen and progesterone receptor status is critical to plan optimal treatment for breast cancer." (PMID 17519044, 2007). "Several but not all previous studies have shown that a high tissue level of IGFBP-3 is related to unfavorable prognostic factors of breast cancer, such as large tumor size, elevated S-phase fraction, elevated DNA aneuploidy, and low levels of ER or progesterone receptor." (PMID 17210081, 2007). "Interestingly, Faivre and co-workers recently reported that the Wnt pathway can be upregulated by the progesterone receptor in breast cancer." (PMID 17245340, 2007). "However, induction of progesterone receptor expression by E2 was impaired in the tissue taken from BRCA1 and BRCA2 carriers compared to that taken from women at population risk of breast cancer." (PMID 16538216, 2006). "The superior prognosis seen with a HRT-associated expression pattern, also validated in a separate cohort of patients with breast cancer, remained stable even after adjusting for Elston grade, lymph node status, progesterone receptor status, tumor size, treatment, and age." (PMID 16813654, 2006). "COX-2 expression has been reported in a significant proportion of preinvasive and invasive breast cancers, and different frequencies of COX-2 over-expression have been observed in subgroups of breast cancer patients by hormone receptor status (estrogen receptor [ER] and progesterone receptor [PR])." (PMID 17181859, 2006). "The aim of this study was to examine the hypothesis questioning the relationship between oestrogen and progesterone receptor status and breast tissue weight in postmenopausal women who had mastectomy for operable breast cancer." (PMID 15904529, 2005). "Progesterone receptor is a prognostic marker in breast cancer." (PMID 16106246, 2005). "A recently published comprehensive analysis of hormone receptor immunochemistry in 450 breast cancer patients confirmed these observations in a larger cohort and speculated on a possible hypothesis for the mechanism of changes in ER and PgR status after PST." (PMID 15611798, 2005). "As for risk of relapse, several subsequent editions of the St.Gallen guidelines, widely accepted as a reasonable approach to the treatment of early breast cancer, rule out that patients with ER/PgR-negative can be considered at minimal risk." (PMID 15790416, 2005). "It has been postulated that joint oestrogen (ER) and progesterone receptor (PR) status might define aetiologically distinct subtypes of breast cancer." (PMID 14583766, 2003). "Interestingly, we found in our series of early-stage breast cancers that the association of uPA–PAI-1 complex and progesterone receptor expression predicted a significantly higher incidence of axillary node metastasis." (PMID 12556966, 2003). "It is concluded that PS2 status may be used as a parameter, additional to ER and PgR, for better refinement of prediction of response to tamoxifen treatment in advanced breast cancer patients especially with intermediate ER/PgR levels in their primary tumour." (PMID 7981080, 1994). "Furthermore, we performed immunohistochemical staining on the organoids at the end of the observation period and compared their molecular marker expression patterns with the parental breast cancer tissue, except for estrogen receptor(ER) and progesterone receptor(PR) markers." (PMID 40087289, 2025). "In breast cancer, PDOs have been shown to preserve the histological and molecular characteristics of the original tumors, including key markers such as estrogen receptor (ER), progesterone receptor (PR), and HER2, copy number variations, and sequence alterations." (PMID 40710388, 2025).
breast cancer (continued). "Quadruple-negative breast cancers (also known as AR-triple negative (TN) BC) lack the expression of estrogen receptor (ER), progesterone receptor (PR), human epidermal growth factor receptor 2 (HER2), and androgen receptor (AR)." (PMID 40448099, 2025). "Despite only accounting for about 15–20% of all breast cancers (BCs), the hormone receptor (HR)-negative subtype, that is, estrogen receptor (ER) and progesterone receptor (PgR) negative, causes a disproportionate number of BC-related deaths the first 5 years after diagnosis." (PMID 40235390, 2025). "The majority of tumors expressed estrogen receptor (ER), progesterone receptor (PR), or both; however, 26.6% of BC patients were classified as a triple-negative breast cancer (TNBC)." (PMID 39596374, 2024). "Triple negative breast cancer (TNBC) is characterized by the lack of human epidermal growth factor receptor-2 (HER2), estrogen receptor and progesterone receptor expression, accounting for 10%–20% of all BC patients." (PMID 39296933, 2024). "Adjuvant treatment with aromatase inhibitors (AI) in oestrogen receptor-positive and/or progesterone receptor-positive breast cancer (BC) has been shown to increase overall survival." (PMID 38774562, 2024). "Breast cancer is a heterogeneous disease that can be classified into molecular subtypes based on histologically determined markers, largely the expression status of the estrogen receptor (ER), progesterone receptor (PR), as well as human epidermal growth factor (HER2)." (PMID 39518898, 2024). "Breast cancer (BC) is a heterogeneous disease consisting of several different subtypes that, until recently, was classified according to the presence of estrogen receptor (ER), progesterone receptor (PR) and/or human epidermal growth factor receptor 2 (HER2) hormone receptors." (PMID 39769392, 2024). "Breast cancer is a genetically and clinically heterogeneous disease that is clinically classified into four subtypes by the expression of receptors, such as the estrogen receptor (ER), progesterone receptor (PR), and human epidermal growth factor receptor 2 (HER2)." (PMID 38474369, 2024). "Breast cancer could be classified into multiple molecular subtypes according to various criteria, based on expression of estrogen receptor (ER), progesterone receptor (PR) and human epidermal growth factor receptor 2 (HER2) or transcription of PAM50 gene signatures." (PMID 39252976, 2024). "Additionally, “catalytic domain”, “progesterone receptor”, “triple-negative breast cancer”, “specific llama-derived antibodies”, “signaling mediate”, and “mesenchymal stromal cell” demonstrated the mechanistic applications of breast cancer-like organs." (PMID 39253075, 2024). "To evaluate whether this data-driven cutoff may be generalisable to other cohorts and thus a feasible clinical strategy, we assessed the distribution of ESR1 and PGR expression in an independent cohort of metastatic breast cancer that includes GEX data from primary tumours and distant metastases." (PMID 38587062, 2024). "Thus, in clinical practice, a surrogate classification of luminal breast cancer is widely performed based on immunohistochemical evaluation for ER, progesterone receptor (PR; an oestrogen‐response marker) and Ki67 (a proliferative marker), serving as important criteria for therapy decisions." (PMID 38282415, 2024). "Breast cancers can be divided into molecular subtypes, which is based upon the genetic profile of the cancers, but in practice is usually based upon the expression levels of the estrogen receptor (ER), progesterone receptor (PR), human epidermal growth factor receptor 2 (HER2) and Ki-67." (PMID 36949047, 2023).
breast cancer (continued). "Breast cancer can be diagnosed by histological methods and can be divided into several types depending on their molecular markers: hormone receptor (HR), including estrogen receptor (ER) and progesterone receptor (PR), and human epidermal growth factor receptor 2 (HER2)." (PMID 36810560, 2023). "The complexity of breast cancer has led to the development of specialized treatment regimens that are dependent on tumor stage, grade, and the presence or absence of hormone receptors (HR; estrogen receptor (ER) and progesterone receptor (PR) and human epidermal growth factor receptor 2 (HER2))." (PMID 37128318, 2023). "Our study reveals that unlike ESR1, PGR is associated with gene silencing in canine mammary tumors." (PMID 37034591, 2023). "Targeted therapies to inhibit estrogen receptor (ER) and progesterone receptor (PR) signaling (selective ER modulators, aromatase inhibitors and selective PR modulators) have shown great promise for the treatment and prevention of hormone receptor (HR)-positive breast cancer." (PMID 37583424, 2023). "Serum circulating miR-200c-3p levels were lower in triple-negative breast cancer (TNBC) patients compared to estrogen receptor (ER)- and progesterone receptor (PgR)-positive BC patients." (PMID 36900200, 2023). "The proposed algorithm was used to select optimal quantile biomarkers of breast cancer progression based on cancer cells’ cell signal intensity levels of nuclear protein Ki-67, Proliferating cell nuclear antigen, Programmed cell death 1 ligand 2, and Progesterone receptor." (PMID 37481512, 2023). "Resistance-associated proteins were Caveolin-1, PgR, mTOR, phosphorylated MEK1/2 (pSer217/221) of the Erk/MAPK signaling pathway, phosphorylated IKKα (pThr23) of the NFκB pathway, the microtubule-associated protein Tau and the basal breast cancer markers CK5, CK6 and Vimentin-pSer56." (PMID 37596623, 2023). "In addition to ER status, PgR status is also an important marker for breast cancer." (PMID 37684569, 2023). "The number (percentage) of patients with each breast cancer type was as follows: non-invasive, 17 (1.7%); invasive, 950 (95.7%); invasive ductal, 876 (88.2%); estrogen receptor positive (ER+), 740 (74.5%); progestogen receptor positive (PgR+), 594 (59.8%); and HER2+, 251 (25.3%) breast cancer." (PMID 37069366, 2023). "Breast cancer treatment is based on prognostic and predictive factors such as tumor stage, histological grade, proliferation, the pattern of hormonal receptor expression (ER, estrogen receptor; PgR, progesterone receptor) and HER2 amplification (Human epidermal growth factor receptor 2)." (PMID 37705026, 2023). "Importantly, there is functional crosstalk between the estrogen receptor and other steroid hormone receptors, such as the progesterone receptor (PR), glucocorticoid receptor (GR), and androgen receptor (AR) in breast cancer cells, as well as other cancer cell types, like endometrial." (PMID 37835383, 2023). "PREDICT scores and the expected breast cancer-associated mortality were calculated according to algorithm v 2.2., including variables for diagnosis age, tumor grade and size, lymph node and HER2 status, adjuvant therapy, and further adjusted for progesterone receptor expression." (PMID 37173335, 2023). "The most common breast cancer (BC) subtypes are hormone-dependent, being either estrogen receptor-positive (ER+), progesterone receptor-positive (PR+), or both, and altogether comprise the luminal subtype." (PMID 36045911, 2022). "Interestingly, but not surprisingly, further analysis showed an increased survival rate among women with ER-positive and PgR-positive breast cancer relative to both receptors’ negative variants (respectively)." (PMID 35627114, 2022).
breast cancer (continued). "The progesterone receptor (PR) is a key player in major physiological and pathological responses in women, and the signaling pathways triggered following hormone binding have been extensively studied, particularly with respect to breast cancer development and progression." (PMID 36076907, 2022). "Similarly, breast cancer cell lines are very heterogeneous and defined in part by differences in their mutational status in the breast cancer tumor suppression gene (BRCA1), estrogen receptor (ER), progesterone receptor (PR), and human epithelial receptor 2 (HER2)." (PMID 34371784, 2021). "Disruption of the proper functioning of steroid hormone receptors, such as the ESR or PGR, may lead to the development of diseases: bone disorders (osteoporosis in humans), tumors (mainly breast cancer), heart and circulatory system diseases, and polycystic ovary syndrome (PCOS)." (PMID 33810503, 2021). "There are four subtypes of breast cancer (BC) that are based on the status of the estrogen receptor, progesterone receptor, and human epidermal growth (Her2) expression in cancerous breast cells." (PMID 34482363, 2021). "Also, high CCL8 expression was remarkably associated with negative Progesterone Receptor, negative Estrogen Receptor and Triple-negative breast cancer subgroup." (PMID 34160019, 2021). "Contrarily, low expression of the lncRNA T cell leukemia/lymphoma 6 (TCL6) in breast cancer has been associated with worse prognosis in progesterone receptor (PR)-negative patients, attributed in part to tumor immune-escape, via regulation of immune-related pathways such JAK/STAT cascades." (PMID 34943820, 2021). "As a disease with complex heterogeneity, TNBC not only lacks the expression of estrogen receptor, progesterone receptor and human epidermal growth factor receptor-2 at hormone level, but also shows more diversity at molecular genetic level compared with other subtypes of breast cancer." (PMID 34858165, 2021). "Tumor gene expression profiling characterizes breast cancer prognosis and chemotherapy response, as demonstrated by a randomized trial of the 21-gene recurrence score (RS) in early stage estrogen receptor and/or progesterone receptor (ER/PR)–positive, HER2-negative disease." (PMID 33426465, 2021). "Triple-negative breast cancers (TNBC) are an heterogenous BC subtype that lack the expression of estrogen receptor (ER), progesterone receptor (PR), and epidermal growth factor receptor 2 (HER2)." (PMID 34831367, 2021). "A treatment choice for breast cancer has recently been determined based on the current standard clinicopathological biomarkers, including the expression levels of hormone receptors (HRs; ER and progesterone receptor [PgR]), human epidermal growth factor receptor 2 (HER2), and Ki67." (PMID 33259001, 2021). "First, ERα(−)/PgR(+) BC is extraordinarily rare and is molecularly, morphologically, and clinically similar to triple-negative breast cancer." (PMID 34638241, 2021). "As already discussed, treatment decision for patients with breast cancer is based on prognostic clinical-pathological parameters (e.g., age, tumor size, presence of node metastases and histological grade), in addition to predictive factors for response to the treatment (ER/PgR and HER2)." (PMID 33953847, 2021). "Five-year adjuvant treatment of women with breast cancer positive for estrogen receptors (ERs) with tamoxifen reduces breast cancer mortality of about one third every year, irrespectively from age, use of chemotherapy, progesterone receptor status, or other tumor characteristics." (PMID 34066685, 2021). "Moreover, an instance where SALL1 influences gene operation is already known: its role as a tumor suppressor in breast cancer, which is downregulated in estrogen receptor, progesterone receptor, and epidermal growth factor receptor-2 “triple negative” breast cancer patients." (PMID 35707773, 2021).
breast cancer (continued). "Triple-negative breast cancer (TNBC), which accounts for approximately 15% of all BC, lacks oestrogen receptor (ER) and progesterone receptor (PR) expression and human epidermal growth factor receptor 2 (HER2) amplification." (PMID 33832512, 2021). "BC expressing hormone receptor (estrogen receptor (ER+) or progesterone receptor (PR+)), BC expressing human epidermal receptor 2 (HER2+), and triple-negative breast cancer (TNBC) (ER−, PR−, HER2−) has been categorized based on histological evidence." (PMID 34659414, 2021). "In clinical diagnosis, breast cancer is classified according to histological grade, Ki-67 proliferative index, and to the expression of hormone and growth factor receptors estrogen receptor (ER), progesterone receptor (PgR), and human epidermal growth factor receptor 2 (HER2)." (PMID 31992741, 2020). "In breast cancers, PD-L1 high/positive expression is associated with larger tumor size, higher tumor grade, increased positive lymph node number, as well as negative ER and progesterone receptor (PR) status." (PMID 32245950, 2020). "As most breast cancers are found in older, postmenopausal women, a reasonable but not widely considered explanation is it that PgR assays in these women are compromised because their low endogenous levels of estradiol are insufficient to elevate PgR levels, even when ER is active." (PMID 32718075, 2020). "Triple negative breast cancer (TNBC) is a subtype of BC that is characterized by transformed cells that lack expression of estrogen receptor (ER), progesterone receptor (PR) and human epidermal growth factor receptor 2 (HER2)." (PMID 31489110, 2019). "In conclusion, we observed significant changes in ERG, PRG and PAG expression in ER+ breast tumours during the menstrual cycle that may affect the assessment and interpretation of prominent biomarkers (e.g. PgR) and commonly used multigene prognostic signatures in premenopausal ER+ breast cancer." (PMID 31754627, 2019). "Traditional classification systems of breast cancer are based on various biological characteristics, including histological grade, tumor size, lymph node involvement, estrogen receptors (ER), progesterone receptors (PGR), and human epidermal growth factor receptor 2 (HER2) status." (PMID 31579605, 2019). "At present, breast cancer can mainly be classified into four primary subtypes, including her2-enriched, luminal A, luminal B, and basal-like, distinguished by the expression of some signature genes such as the estrogen receptor (ER), progesterone receptor (PR), and HER2." (PMID 31466383, 2019). "Therefore, regardless of the diagnostic criteria or the process for preparing specimens, we may find ER−/PgR+ breast cancer cases in our routine practice." (PMID 30066060, 2019). "The main subtypes of breast cancer are divided by the expression statuses of three tumor markers evaluated comprehensively and routinely because of their application in guiding clinical treatment: estrogen receptor, progesterone receptor and human epidermal growth factor 2-neu (HER2)." (PMID 31871847, 2019). "Breast cancer (BC) comprises several subtypes that are in clinical routine defined by estrogen receptor (ER), progesterone receptor (PR), and human epidermal growth factor receptor 2 (HER2) status." (PMID 30301470, 2018). "In breast cancer cells, overexpression of a synthetic miR-423-5p inhibits the expression of the Progesterone Receptor (PGR) gene, a prognostic marker of breast cancer, by reducing RNA polymerase II binding and enriching silent chromatin markers on PGR gene promoter." (PMID 29401683, 2018). "In Vietnam, the main means of detecting breast cancer cited in the literature include ultrasound, hemotogram, CA 15.3, tumour biopsy or cytological tests with some women having mammography and oestrogen-receptor tests, progesterone receptor tests and Her 2-Neu tests." (PMID 29473488, 2018).